IL1B (interleukin 1 beta)
Diseases named in the same sentence as IL1B in open-access papers (continued):
Sharing a sentence is not in itself a finding about the gene and the disease.
infection (continued). "However, we observed limited changes in other key inflammatory response markers (e.g., il1b) therefore it is difficult to speculate the influence of temperature changes on inflammatory responses following infection." (PMID 39560796, 2024). "Interestingly, in the later stage of infection, the IL-1β mRNA expression level was negatively correlated with the infected dose, which may have been due to the longer duration of action of the virus at lower doses." (PMID 39767659, 2024). "Therefore, we hypothesize that there might be alternative pathways for producing IL-1β upon SVV infection." (PMID 39038050, 2024). "However, Telaglenastat treatment dampened IL1-β secretion at 48 and 72 hours after infection." (PMID 39605528, 2024). "S10 effectively inhibited the secretions of IL-1β and TNF-α in an in vitro inflammatory model of infection induced by P. gingivalis and demonstrates that S10 effectively suppresses the P. gingivalis infection-induced secretions of the pro-inflammatory cytokines IL-1β and TNF-α by THP-1 macrophages." (PMID 38921772, 2024). "Given the significance of IL-1β as a key cytokine for protection against TB, and the ability of Mtb to evade inflammasome-dependent surveillance mechanisms in MФs, first we used wild-type C57Bl/6J mouse bone marrow-derived APCs for infection experiments, followed by cytokine assays." (PMID 38975346, 2024). "In contrast, infection of zebrafish larvae with LD of L. pneumophila WT leads to a short induction of Il1b transcript levels at 6 hpi before declining to control levels at later time points, suggesting that a short boost of IL-1β is sufficient to control LD of L. pneumophila." (PMID 37155695, 2023). "IL-1β is responsible for immune responses to infections and regulates a broad range of proinflammatory activities in immune cells, including the induction of rapid neutrophil recruitment at infection sites, endothelial adhesion molecule activation, and inducing chemokine production." (PMID 36680196, 2023). "Therefore, neutrophil recruitment to the T. gondii-infected human retinal pigment epithelium cells, enhanced by IL-1β, may play an important role in the pathogenesis of the infection." (PMID 38983057, 2023). "Notably, IL-1β has been identified as a significant signaling factor for host resistance against infection, as this cytokine transmits signals through IL-1R and myeloid differentiation primary response protein (MyD) 88, leading to the induction of NOS2-mediated nitric oxide (NO) production." (PMID 38097942, 2023). "During infection, the expression of IL-1β begins to decrease gradually, indicating that N. seriolae may inhibit the inflammatory response for survival by downregulating the expression of IL-1β, which is similar to that observed in Listeria, Salmonella, and M. tuberculosis." (PMID 36926518, 2023). "Since the duration of in vitro infection in this study did not exceed 12 h, these data suggested that the excessive secretion of IL-1β may not be caused by pyroptosis." (PMID 37978190, 2023). "Moreover, we found that infection with SARS-CoV-2 GFP/ΔN induced inflammatory cytokines such as IL-1β and TNF-α mRNA expression, all of which could be prevented by 17-DMAG." (PMID 37011862, 2023). "Therefore, the already in-place blockage of the inflammasome-IL-1β axis and the effect exerted by vaccination could have protected these patients more from developing a major infection and, in turn, from hyperinflammation." (PMID 37510856, 2023). "Transcripts encoding the inflammatory cytokines, TNF-α, IL-1β and IL-6, were not consistently detected in monolayers subjected to mock infection with medium alone, but infection with all of the DENV isolates stimulated IL-6 expression, although notably higher levels were seen with DENV2 strains." (PMID 37515098, 2023).
infection (continued). "In addition to the 72 hpi timepoint used for RNA-seq, we found that infection with so/sp Mtb elicited significantly higher levels of expression of Il1b, Nos2, Il6, and Tnf at 6 and 24 hpi by qPCR compared with 5μmF preparations, with the greatest difference seen early in infection." (PMID 36852737, 2023). "In addition, infection with S17 was associated with a reduced inflammatory response, including reduced bronchoalveolar lavage fluid (BAL) polymorphonuclear (PMN) cell count, and reduced BAL TNF, IL-1β, and IL-12p40 levels." (PMID 37056705, 2023). "Furthermore, 1,25D3 is known to boosts infection-stimulated cytokine/chemokines, a critical component of the macrophage response to Mycobacteria marinum infection, and 1,25D directly upregulates IL-1β gene transcription in macrophages." (PMID 37238716, 2023). "At 24 h postinfection, the Δgroup5437 and Δgroup6178 infection groups exhibited significantly higher levels of IL-10 (an anti-inflammatory cytokine) than the WT group; however, these two groups simultaneously showed higher levels of induction of proinflammatory mediators (IL-1β and iNOS)." (PMID 37191575, 2023). "In addition, IL1β and other unconventional secretory proteins are found to be efficiently secreted upon infection-induced permeabilization of the plasma membrane of immune cells, suggesting a substantial fraction of these cargo molecules are located in the cytoplasm of immune cells." (PMID 37931110, 2023). "Moreover, it is unclear whether A1 upregulation is beneficial or deleterious for the host during infection, since this may be multi‐factorial depending on the pathogen, cell types involved, and the role IL‐1β plays in shaping the immune response." (PMID 37846472, 2023). "Unexpectedly, we revealed a statistically significant, CARD8-dependent increase in IL-1β as early as 2 hr after infection (the first timepoint assayed after the initial infection), which plateaued for the next 6 hr and then further increased by 24 hr post-infection." (PMID 37417868, 2023). "Our study serves as a proof of concept model identifying aggregated C protein as a possible novel agonist for NLRP3 inflammasome activation and IL-1β secretion during Hendra virus infection that may contribute to increased detrimental inflammation during in vivo infection." (PMID 37950278, 2023). "Additionally, in contrast to anti-viral agents that require early intervention, we show that neutralization of IFN-γ and TNF, or IL-1β activity in the aftermath of infection can serve as “pro-repair strategies” to augment alveolar regeneration and dampen fibrotic sequelae." (PMID 38077031, 2023). "To test whether macrophages could produce soluble signals required to activate NK cells during infection, we established an in vitro model to mimic L. monocytogenes infection in macrophages and measured IL‐1β and IL‐18 secretion in the supernatant of infected cells." (PMID 36861806, 2023). "However, the immune response in the liver at late stages of the primary infection exerted a mixed Th1/Th2 response including the participation of cytokines such as IL-1β, TNF-α, TGF-β and IL-4 as it has been reported during acute and chronic stages in ruminants and other species." (PMID 36627694, 2023). "When we used the pancaspase inhibitor Z-VAD, IL-1β secretion was lower (550.1 pg/mL) during the infection with the NADL cp strain, which could suggest the involvement of other caspases in the secretion of IL-1β; in the case of the NY-1 ncp strain, there was no statistical significance." (PMID 37515181, 2023). "The downregulation of TNF-α and IL-1β genes may indicate aggressive virulent behavior of P. aeruginosa and F. oxysporum, which might have suppressed or delayed a ubiquitous immune response to a robustly developing infection." (PMID 37569767, 2023). "Hence, we attempted to explore whether the Del2R infection enhances IL-1β and TNF-α production in vivo." (PMID 37566637, 2023).
infection (continued). "Therefore, the concerted action of IL-1β and IL-8 at infection sites may drive the massive infiltration of lymphocytic inflammatory cells that has been consistently observed in multiple organs including the brain, liver, intestines and spleen, during TiLVD." (PMID 37622112, 2023). "For example, BCG-induced genome-wide epigenetic reprogramming in monocytes are proved to protect humans from experimental infections from yellow-fever attenuated vaccine strains, which may be critical for monocyte-produced IL-1β function to achieve a protective effect." (PMID 36765373, 2023). "A deeper look into the brain showed elevated IL-1β in combination with reduced expression of growth factors, which ultimately prohibited proliferation of neural stem cells (NSCs) as early as 4 days post infection (dpi), and decreased neurogenesis at 34 dpi in the hippocampus." (PMID 37649972, 2023). "It is tempting to speculate that the STEC type III secretion system (T3SS) is implicated since our results indicated that NLRP3 is involved in IL-1β secretion, and previous studies showed that Salmonella enterica induces NLRP3 activation upon THP-1 infection associated with the activity of the T3SS." (PMID 38127952, 2023). "Interestingly, we detected an upregulation of Il1b for both GAS mono-infection and superinfection, which suggests that the incapacity of co-infected macrophages to process and secrete IL-1β is due to a failure in the GAS-inducible activation of the NLRP3 inflammasome." (PMID 36365071, 2022). "The reduction in IL-1β could be explained by the decrease in macrophages early during infection." (PMID 36040164, 2022). "As a result, the concentration of IL-1β could indicate the body infection." (PMID 35847636, 2022). "Again, in line with our hypothesis of exaggerated responses to lung infection, many of the top upstream regulators identified by IPA were associated with enhanced inflammation (TNF, IFNG, and IL1B) and infection with Gram-negative bacteria (TLR4)." (PMID 36264633, 2022). "Likewise, chickens infected with MDV/CVI988 at 7 and 14 dpi showed significantly increased levels of IL-1β in the bursa compared with the uninfected control chickens, but the MDV/RB1B infection-induced upregulation of IL-1β transcription lasted from 7 to 28 dpi." (PMID 36680047, 2022). "The plasma levels of IL-1β were significantly increased in T. cruzi-infected WT and Il-1r−/− mice compared to respective noninfected controls at 210 dpi, demonstrating that the secretion of this cytokine is stimulated and remains elevated long after infection onset." (PMID 36341442, 2022). "Moreover, infection by Escherichia coli releases lipopolysaccharide, which leads to further activation of inflammasomes and releases pro-inflammatory cytokines and interleukin (IL)-1β, which also enhances inflammation." (PMID 35720309, 2022). "Regarding the cell-mediated response related genes, NCCRP-1, TCR-γ, CD4, and CD8 were up-regulated in the sea bass brain with higher levels of NCCRP1 and TCR-γ upon infection with the mutant isolate at 3 dpi, which could be related to the up-regulation of IL-1b." (PMID 35215144, 2022). "Interestingly, IL-1β is well-known for its key role in the activation and amplification of inflammatory signaling cascades, recruitment of other immune cells to the site of infection, and enhancement of intracellular killing." (PMID 36311802, 2022). "Furthermore, support for this hypothesis was obtained by monitoring the cleavage and secretion of the inflammasome-dependent cytokine, IL-1β, upon infection with V. proteolyticus strains." (PMID 36155655, 2022). "These and other cytokines involved in the immunopathology of acute patients such as IL-1β and IL-10 could be fundamental for the discrimination of the outcome of the infection as they have been seen to be significantly higher in severe than in mild forms of the disease." (PMID 36079033, 2022). "The higher the levels of IL-1β and IL-6, the more serious the infection may be." (PMID 35531475, 2022).
infection (continued). "Moreover, Mtb-mediated AIM2 inflammasome inhibition is dependent on a functional ESX-1 secretion system since infection with the Mtb strain deficient in esxA fails to inhibit IL-1β secretion induced by Msme." (PMID 35237260, 2022). "However, IL-1β signaling is merely one downstream pathway activated by NLRP3, and the complete inhibition of IL-1β signaling may increase the risk of fatal infection in clinical treatment." (PMID 35883561, 2022). "However, the decreased release of IL-1β was evident only after 3 h of coincubation with the ktr3Δ cap6Δ strain, suggesting that O-glycans of C. neoformans are partly involved in triggering pyroptosis, which appears to occur early during infection." (PMID 36409123, 2022). "As expected, AIM2 deficiency sharply reduced IL-1β secretion and NLRP3 deficiency could not abolish IL-1β secretion upon infection of the mutant strain." (PMID 36128739, 2022). "These authors reported tilmicosin decreased intracellular infection (p < 0.01), had a protection effect on the mammary epithelial cells reducing apoptosis after infection by 80% (p < 0.01), reduced reactive oxygen species (p < 0.01), IL-1β (p < 0.01), IL-6 (p < 0.01) and TNF-α (p < 0.05)." (PMID 36557690, 2022). "Infection with cagA-positive strains can be led to gastric mucosal inflammation, which in turn increases the diffusion of antibiotic (following an increase in blood flow, disruption of mucosal barrier, and inhibition of IL-1β-induced gastric acid secretion) and ultimately high cure rate." (PMID 35752757, 2022). "However, during immune responses, neutrophils are massively recruited to the site of infection and inflammation, which may compensate for the limited amount of IL-1β produced per neutrophil as compared with macrophages." (PMID 35406754, 2022). "In this study, concentrations of IL-1β and TNF-α in bMECs culture medium increased significantly after bMECs were infected with K. pneumoniae; furthermore, there was a positive association with duration of infection time, confirming K. pneumoniae-induced inflammation of bMECs." (PMID 33468111, 2021). "The expression of il1b, which had the strongest upregulation in untreated cells after infection with both NmB strains (65-fold by the wild type, 78-fold by MC58saiD−), is upregulated only 57-fold by MC58saiD− when Erk1/2 signalling was inhibited during infection." (PMID 34863201, 2021). "Therefore, it may be that in our study, human macrophages are able to engage relatively rapid pathways facilitating IL-1β secretion in spite of early cell death when infected with early infection P. aeruginosa isolates." (PMID 33664232, 2021). "However, another study found that IL-1β-deficient mice were protected from developing UPEC mediated UTI, which suggests that IL-1β may drive the infection." (PMID 34944029, 2021). "Chiang and coworkers demonstrated that NNV infection of the primary culture of brain cells from giant grouper (Epinephelus lanceolatus) activates microglial cell proliferation and secretion of proinflammatory cytokines (IL-1β and TNF-α) and subsequently the neural cell death." (PMID 34707620, 2021). "Measurement of serum creatinine, SAA, and pro-inflammatory cytokines (serum baboon and pig IL-6 and IL-1β) in baboon recipients may prove useful in indicating whether a baboon recipient is developing rejection or infection, though it might be insufficient to distinguish conclusively between the two." (PMID 34956220, 2021). "Additionally, the S. Typhi ΔtviA and tviA-REP mutant strains induced higher levels of caspase-1, IL-1β, and gasdermin D cleavage as assessed by Western blot compared to the WT S. Typhi strain, indicating greater inflammasome activation upon infection with these mutants." (PMID 33651854, 2021). "We hypothesized that defects in IL-1β production may lead to susceptibility to infection in the absence of GSDMD." (PMID 34011393, 2021).
infection (continued). "Moreover, patients with active paracoccidioidomycosis presenting with high levels of IL-1β and IL-18 in the serum that return to normal levels in response to antifungal therapy indicate that these cytokines are released during active infection with this pathogen." (PMID 34769275, 2021). "Except for IAVs, several studies have demonstrated the essential role of endogenous Gal-3 in infection-induced inflammatory response against either virus or bacteria invasion via inducing neutrophil infiltration or proinflammatory cytokine production such as IL-1β, TNF-α, and IFN-γ." (PMID 34065500, 2021). "Thus, the induction and inhibition of TNF-α and IL1-β produced by mint oils controls the inflammatory response to inflammation against infection and might be beneficial to the host." (PMID 34201645, 2021). "The resultant local inflammation attracts an influx of immune cells to a site of infection, hence IL-1β release in BU could impact the ability of the host to respond to M. ulcerans infection, by enhancing the activation state of surrounding cells, including innate immune macrophages and neutrophils." (PMID 35154073, 2021). "Upon infection, cardiac-resident cells, such as cardiomyocytes, endothelial cells, and fibroblasts, may contribute to acute inflammation by secreting cytokines such as IL-1β, IL-6, TNF-α, and IL-18." (PMID 34504807, 2021). "However, in other studies, genetic deficiency or neutralization of IL-1α, but not of IL-1β, conferred higher susceptibility to infection." (PMID 34809460, 2021). "Whether this reduced IL-1β mRNA expression is caused by epigenetic modifications in monocytes or by attenuated infection due to increased resistance is currently not know." (PMID 34601443, 2021). "Infection with the toxigenic strain of S. hyicus induced both an inflammatory reaction and an anti-inflammatory response as indicated by the cytokine assay results—a significant increase in the levels of a pro-inflammatory cytokine (IL-1β) and an anti-inflammatory cytokine (IL-10)." (PMID 33665221, 2021). "Similarly, IL-1β mRNA levels increased by 400-fold by day 5 after infection." (PMID 33477869, 2021). "We suspect that human GWAS studies for IL-1β may be susceptible to false negative findings, as IL-1β levels have a large environmental component due to its response to infection or inflammation." (PMID 34197316, 2021). "On the other hand, F. nucleatum subsequential infection maintained the secretion levels of IL-1β, IL-6 and TNF-α in pulmonary epithelial cells compared to the single P. aeruginosa group, which may be due to the low cellular viability caused by P. aeruginosa pretreatment." (PMID 33816348, 2021). "However, manipulation of these defenses and damage by the infection may lead to aberrant responses characterized by the unchecked release of pro-inflammatory cytokines such as IL-1α, IL-1β, TNFα, IFN-γ, and IL-6." (PMID 34440903, 2021). "Similarly to IL1β, IFNγ is also an important mediator of the immune response to infection but when chronically elevated may have important immunopathological consequences." (PMID 33182721, 2020). "Interestingly, in Nlrc4–/– mice, IL-1β and KC levels in target tissues are elevated, indicating that Shigella may encounter multiple inflammasomes at distinct stages of infection with opposing consequences for bacterial replication and host pathogenesis." (PMID 33074100, 2020).